HAL (histidine ammonia-lyase)
Synonyms: HIS; HSTD
Tractability: PROTAC: ubiquitination databases record sites on it; its protein half-life has been measured.
Target class: Enzyme; Lyase
Gene: Protein-coding gene on chromosome 12 (95,972,662 to 95,996,365, reverse strand). Ensembl gene ENSG00000084110.
Subcellular location (Human Protein Atlas): Cytosol
Pathways (Reactome):
Metabolism: Histidine catabolism
Gene Ontology:
Molecular function: histidine ammonia-lyase activity; protein binding; ammonia-lyase activity; catalytic activity
Biological process: L-histidine catabolic process; cellular response to nutrient
Cellular component: cytosol; cytoplasm
Genetic constraint (gnomAD): Loss-of-function variants: 54 observed, 55.87 expected, observed/expected ratio (o/e) 0.97, 90% interval 0.78 to 1.21. The upper end of that interval is the gene's LOEUF score, 1.21, which puts it in group 5 of 6, group 1 being the genes least tolerant of losing a copy. Missense variants: 609 observed, 643.27 expected, observed/expected ratio (o/e) 0.95, 90% interval 0.88 to 1.01. Synonymous variants: 226 observed, 244.73 expected, observed/expected ratio (o/e) 0.92, 90% interval 0.83 to 1.03.
Gene-disease validity (ClinGen):
ClinGen rates the evidence that HAL causes each of these diseases.
histidinemia (autosomal recessive): Limited. Histidinemia is a rare metabolic disorder characterized by elevated histidine levels in blood, urine, and cerebrospinal fluid, generally with no clinical repercussions.
Homologues: Orthologues: chimpanzee HAL (99% identical), macaque HAL (98% identical), rabbit HAL (95% identical), dog HAL (95% identical), pig HAL (95% identical), rat Hal (94% identical), mouse Hal (94% identical), guinea pig HAL (93% identical), tropical clawed frog hal.2 (85% identical), zebrafish hal (80% identical), Caenorhabditis elegans haly-1 (53% identical).
Diseases named in the same sentence as HAL in open-access papers:
HAL is named in the same sentence as 26 diseases in open-access papers, as found by Europe PMC text mining. Sharing a sentence is not in itself a finding about the gene and the disease. The quoted sentences say what the papers report.
histidinemia (4 papers, 2014 to 2025). "Missense mutations of the HAL gene cause histidinemia, which is the most frequent inborn metabolic error in Japan." (PMID 41002986, 2025). "Similarly, whereas mutations in HAL are known causes of histidinemia, the mutations we highlight in association with plasma histidine levels in FHS are novel." (PMID 27453504, 2016).
breast carcinoma (3 papers, 2020 to 2022). "Our results show that low expression of HAL is associated with improved survival in HER2-positive breast cancer, suggesting that inhibition of tumor cell metabolism may be beneficial for tumor prognosis." (PMID 35663326, 2022). "Compared with normal control tissues, the expression of HPRT1, ASNS, ATIC, SULT1A2, and HAL was significantly increased in HER2-positive breast cancer samples." (PMID 35663326, 2022). "Importantly, in HER2-positive breast cancer, decreased expression of metabolism-related genes ATIC, HPRT1, ASNS, SULT1A2, and HAL was associated with increased survival." (PMID 35663326, 2022). "Finally, high expression levels of HAL contributed to poor prognoses in breast cancer patients." (PMID 33381521, 2020). "In addition, ATIC, HPRT1, ASNS, SULT1A2, and HAL may represent attractive therapeutic targets for HER2-positive breast cancer, and require further validation studies, especially considering that treatment with specific inhibitors may alter the expression of these metabolic genes." (PMID 35663326, 2022).
liver cancer (2 papers, 2022 to 2024). An epithelial or non-epithelial malignant neoplasm that arises from the liver. "Although we previously showed that histidine ammonia lyase (HAL) was transcriptionally reduced by the β-catenin/TCF complex in liver cancer cells, the mechanism(s) of its down-regulation by the complex remain to be clarified." (PMID 38684876, 2024). "We find significantly lower expression of the Neanderthal allele in liver cancer compared to unaffected livers and overall lower expression of HAL in liver cancer and unaffected livers." (PMID 36503519, 2022). "In this study, we have shown that the promoter region of HAL was transcriptionally regulated by transcription factors CEBPA and FOXA1, and that the two were down-regulated by the Wnt signaling pathway in the liver cancer cells." (PMID 38684876, 2024). "We previously uncovered that the 5’-flanking region of HAL, between −90 bp and −44 bp, was responsible for the suppression of β-catenin/TCF complex in liver cancer cells." (PMID 38684876, 2024). "In this study, we clarified that HAL was transcriptionally induced by CEBPA and FOXA1, and that their expression levels were down-regulated by the Wnt/β-catenin signaling in the liver cancer cells." (PMID 38684876, 2024).
melanoma (2 papers, 2020 to 2023). A malignant, usually aggressive tumor composed of atypical, neoplastic melanocytes. "Most notably, with MC1R, CAT and NOS1 genes in melanoma, HAL and IL23A genes in BCC and HAL and XRCC1 genes in SCC." (PMID 37537768, 2023). "Changes in the expression of histidine ammonia lyase may be related to a transition from primary melanoma to metastatic melanoma." (PMID 33108391, 2020). "We found some evidence of GxE interactions with sun exposure, notably, with MC1R, CAT and NOS1 genes in melanoma, HAL and IL23A in BCC and HAL and XRCC1 in SCC." (PMID 37537768, 2023).
basal cell carcinoma (1 paper, 2024). A carcinoma involving the basal cells. "Previous studies about HAL, containing the rs3213737 locus, might play roles in basal cell carcinoma and skin pigmentation." (PMID 39281383, 2024).
colorectal adenocarcinoma (1 paper, 2024). The most common type of colorectal carcinoma. "The down-regulation of HAL and ARG1 by Wnt signaling is likely dependent on the type of tissue because the expression of HAL and ARG1 did not decrease in the Wnt-activated colorectal adenocarcinoma." (PMID 38684876, 2024).
coronary heart disease (1 paper, 2023). "Histidine also has antioxidant activity, and loss of function mutations in human histidine ammonia lyase (HAL), the first enzyme in the catabolic pathway is associated with a reduced hazard of coronary heart disease." (PMID 37918802, 2023).
heart failure (1 paper, 2025). Inability of the heart to pump blood at an adequate rate to meet tissue metabolic requirements. "Since ventricular remodeling is a pivotal process in post-MI heart failure progression, the ability of HAL to attenuate this remodeling highlights its potential therapeutic value." (PMID 41567391, 2025).
leukemia (1 paper, 2022). A malignant (clonal) hematologic disorder, involving hematopoietic stem cells and characterized by the presence of primitive or atypical myeloid or lymphoid cells in the bone marrow and the blood. "Higher levels of HAL expression were found among leukemia patients with higher survival rates." (PMID 36503519, 2022).
metabolic syndrome (1 paper, 2021). A cluster of metabolic risk factors for CARDIOVASCULAR DISEASES and TYPE 2 DIABETES MELLITUS. "The HAL gene was found in gene ontology and has an effect on amino acid metabolism in animals and humans; dietary histidine is related to factors that improve metabolic syndrome and affect ion absorption in human populations." (PMID 34946969, 2021).
ovarian carcinoma (1 paper, 2023). A malignant neoplasm originating from the surface ovarian epithelium. "Our findings indicated that WEE1, PYHIN1, and SEC61A2 served as risk factors impacting the prognosis of ovarian cancer, while HAL demonstrated a protective effect." (PMID 37781709, 2023). "Subsequently, to quantify the survival risk for each ovarian cancer patient, we developed a risk model utilizing a multi-factorial Cox formula based on the four aforementioned genes (WEE1, PYHIN1, SEC61A2, and HAL)." (PMID 37781709, 2023).
pancreatic tumors (1 paper, 2023). "The expression of HAL, an enzyme involved in the His metabolic pathway, was greatly elevated in human and mouse pancreatic tumor tissue." (PMID 37174059, 2023). "We provide evidence that the expression of histidine ammonia lyase (HAL), an enzyme involved in His catabolism, is greatly increased in mouse and human pancreatic tumors." (PMID 37174059, 2023).
skin cancer (1 paper, 2025). "We recently noticed an interesting common variant (MAF = 42%) GWAS hit near the HAL gene (12_95984993_C_T, rs3819817) that was associated both with vitamin D level and skin cancer." (PMID 41004399, 2025). "Unexpectedly, although we anticipated that the effect of the rs3819817 HAL eQTL variant on vitamin D level and skin cancer risk would be mediated by the conversion of histidine to trans-urocanate, the variant had only a weak association with plasma histidine level (beta = −0.014; P = 1.8 × 10−6)." (PMID 41004399, 2025). "Furthermore, the lead variant had a positive effect on HAL expression and trans-urocanate level and a negative effect on vitamin D level, sunburn occurrences, and skin cancer risk." (PMID 41004399, 2025).
tumor (5 papers, 2022 to 2024). "We also assessed the interaction between HAL and hsa-miR-582-3p, which has been previously indicated as a tumor suppressor miRNA in AML." (PMID 36033493, 2022). "Although HAL was over-expressed in PC cells and tissues, it is still unclear whether HAL is an oncogene or a tumor suppressor." (PMID 37174059, 2023). "In contrast, HAL did not exhibit significant differences in mRNA expression between the two sample types, but protein upregulation was evident in tumor samples." (PMID 37781709, 2023). "Conversely, hepatic periportal markers (e.g., ALDOB, HAL, ASS1) and a subset of CYP-related proteins (e.g., CYP2A6, CYP2A7, CYP2B6) were either absent or downregulated in the tumor region." (PMID 39567475, 2024).
cancer (3 papers, 2019 to 2023). A tumor composed of atypical neoplastic, often pleomorphic cells that invade other tissues. "Our study suggests that monocyte-derived biomarkers, specifically WEE1, PYHIN1, SEC61A2, and HAL, hold potential as predictors for cancer prognosis and AMI." (PMID 37781709, 2023). "Most important of all, these findings demonstrate the potential of utilizing shared biomarkers (WEE1, PYHIN1, SEC61A2, and HAL) to predict outcomes in both cancer and AMI patients." (PMID 37781709, 2023). "However, further experimental studies are needed to elucidate the specific roles of WEE1, PYHIN1, SEC61A2, and HAL in disease occurrence, progression, and response to treatment in both cancer and AMI." (PMID 37781709, 2023). "Recently, Naama Kanarek and colleagues reported that histidine ammonia lyase (HAL), the rate‐limiting enzyme of the histidine degradation pathway, contributed to the sensitivity of cancer cells to MTX by competitive consumption of THF." (PMID 30714292, 2019). "In our study, our findings suggest that WEE1, PYHIN1, SEC61A2, and HAL derived from monocytes may serve as a potential predictor for AMI and cancer prognosis." (PMID 37781709, 2023). "In summary, our findings suggest that WEE1, PYHIN1, SEC61A2, and HAL derived from monocytes may serve as a potential predictor for AMI and cancer prognosis." (PMID 37781709, 2023). "Moreover, among this class of targets, there are also some novel candidates whose functions in cancer have not been thoroughly investigated, including three enzymes in the histidine degradation pathway, formimidoyltransferase cyclodeaminase (FTCD), histidase (HAL), and urocanase (UROC)." (PMID 31601242, 2019).
infection (1 paper, 2021). The state of being infected such as from the introduction of a foreign agent such as serum, vaccine, antigenic substance or organism. "There was a significant rise in the expression levels of both HAL and HDC 48 h post infection, in macrophages activated with CD4 T cells or treated with external IFN-γ." (PMID 33767335, 2021). "An increase in the expression levels of HAL and HDC was observed 3 weeks post infection in H37Rv-infected B6 whole lungs lysates." (PMID 33767335, 2021). "In order to examine the effects of HAL and HDC up-regulation on the levels of free histidine, we quantified and compared the levels of free histidine in infected lungs on days 1, 15, 21 and 28 post infections." (PMID 33767335, 2021). "Remarkably, the levels of urocanate remain completely undetected in B6 IFN-γ−/− mice lungs throughout the infection; corroborating with the absence of HAL expression." (PMID 33767335, 2021). "We find that 2 weeks post infection, the host through an interferon gamma (IFN-γ) mediated mechanism upregulates its histidine catabolizing enzymes – histidine ammonia-lyase (HAL) and histidine decarboxylase (HDC), possibly to starve the Mtb of free intracellular histidine." (PMID 33767335, 2021).
metabolic disease (1 paper, 2022). A congenital disorder (due to inherited enzyme abnormality) or acquired (due to failure of a metabolically important organ) disorder resulting from an abnormal metabolic process. "Regarding a VD deficiency, the genes LIPC, HAL, GC and the Cytochrome P450 Family genes were among those which are more strongly associated with nutritional/metabolic diseases." (PMID 36430729, 2022). "Importantly, the LIPC gene was more prominently associated with nutritional/metabolic diseases, with the genes GC, HAL and the Cytochrome P450 Family also being implicated." (PMID 36430729, 2022).
HAL also shares sentences with these, for which no sentence is quoted: bladder cancer (1 paper); Burkitt lymphoma (1); chronic myeloid leukemia (1); glioblastoma (1); hematopoietic cancer (1); metastatic melanoma (1); myocardial infarction (1); Obesity (1); serous ovarian cancer (1).